CEACAM5 (CEA cell adhesion molecule 5)
Diseases named in the same sentence as CEACAM5 in open-access papers (continued):
Sharing a sentence is not in itself a finding about the gene and the disease.
cancer (continued). "Co-culture of metaplastic gastroids with the characteristics of spasmolytic polypeptide-expressing metaplasia with either metaplasia-derived or cancer-derived fibroblasts caused loss of metaplastic markers CD44v9 and AQP5 expression and gain of dysplasia markers TROP2 and CEACAM5 expression." (PMID 37196797, 2023). "Functionalization of the sensor was realized to detect a kind of cancer biomarker—CEACAM5." (PMID 37504073, 2023). "In addition, CEACAM5 is overexpressed in various carcinomas, and it is one of the target genes for HPV gene integration, indicating the role of CEACAM5 as a CC‐associated antigen." (PMID 36967539, 2023). "Data in the CEA model included age at diagnosis, body mass index (BMI), total number of pregnancies, patient smoking history category, tumour type, primary lymph node presentation assessment, neoplasm cancer status and the expression level of CEACAM5, which represents a typical oncofetal antigen." (PMID 33369107, 2021). "CEACAM5 adhesion molecules were reported to be overexpressed in many cancers, including CRC." (PMID 34503224, 2021). "CEACAM5 has also been found to be expressed in a wide variety of cancer." (PMID 33791201, 2021). "Thus, it is highly plausible that CEACAM5 is a marker of epithelial differentiation – in normal breast and in corresponding cancer." (PMID 33196697, 2020). "Interestingly, we also observed that carcinoma cell lines, expressing native forms of CEACAM-5 and CEACAM-6, showed a different profile for expression of the antigen recognized by NEO-201." (PMID 32637350, 2020). "However, elevated expression of CEACAM5 was confirmed in metastatic lesions obtained directly from cancer patients, thus confirming the clinical relevance of our findings." (PMID 29736411, 2018). "Our assessments demonstrated CEACAM5 expression in 5 of 9 non-cancer lung resection samples supporting the hypothesis that MFEζ T cell binding to CEACAM5 antigen present within normal lung may have contributed to this toxicity." (PMID 28660319, 2017). "Thus, there appeared to be strong/intermediate CEACAM5 expression in 5/8 non-cancer lung resection samples." (PMID 28660319, 2017). "Nevertheless, with the IHC of the correlated expression pattern of OPN and CEACAM5 in carcinoma, our data showed that OPN and CEACAM5 may act as a functional complex in these lesions." (PMID 22738781, 2012). "CEACAM5 interacts with CEA-receptor (CEAR) in the cytoplasm of human cancer cells." (PMID 21436956, 2011). "Therefore, when serum CEACAM5 levels are elevated, it means that the body may suffer from cancer, including colorectal, lung, and breast cancers." (PMID 38275310, 2024). "CEACAM5 might become a potential target for a variety of cancer therapies." (PMID 36568638, 2022). "Therefore, CEACAM5 expression may be a means for cancer cells to overcome apoptosis-inducing therapies." (PMID 17201906, 2007). "In this study, we investigated the utility of a novel developed anti-CEACAM5 VHH for cancer diagnosis and its potential of being a targeting-moiety of VHH-drug conjugates for cancer therapy." (PMID 40358697, 2025). "We identified one cluster as the cancer‐pre cells, since it was enriched in the EGC biopsy and expressed cancer markers (CEACAM5 and CEACAM6)." (PMID 40860436, 2025). "Remarkably, the group of cancer-related proteins,i.e., CEACAM1,CEACAM5, and CEACAM6 as well as the minichromosome maintenance complexcomponents MCM3, MCM4, and MCM6 showed clear protein abundance patternsrelated to the radiation response." (PMID 40574313, 2025). "Particularly, cumulative evidence from preclinical and clinical data together revealed a more complex influence, in particular for CEACAM1, CEACAM5, and CEACAM6 on cancer and CSCs." (PMID 41233805, 2025). "CEACAM5, also known as carcinoembryonic antigen (CEA), has been reported to be overexpressed in several cancers, especially colon cancer." (PMID 38738791, 2024).
cancer (continued). "CEACAM1, CEACAM5, and CEACAM6 are the best characterized molecules in cancer processes and are considered valid clinical biomarkers and promising therapeutic targets in melanoma, lung, colorectal, and pancreatic cancers." (PMID 37942534, 2024). "Sacituzumab govitecan led to the validation of TROP2 as a target in TNBC, and SN-38-based ADCs in clinical evaluation highlight the potential of new targets in cancer types that were poorly represented in the ADC landscape (HER3, CEACAM5, B7-H3 and GPR20)." (PMID 36650546, 2023). "In coordination with CEACAM1s ability to downregulate immune cells, CEACAM5 is a binding partner to CEACAM1 that can elicit this signaling, allowing for immune evasion by cancer cells." (PMID 36741860, 2023). "For decades, CEACAM5 (CEA), a member of the same superfamily, has been used as a biomarker to observe the progression of several types of cancer following surgery." (PMID 37965453, 2023). "This heatmap, based on a dataset including samples from NILM, ASC-US, and ≥LSIL groups, displays two main clusters: cancer markers (MCM3, CEACAM5, S100P, ICAM1) on the left and healthy markers (CRNN, EVPL, DSC2) on the right side of the figure." (PMID 37445651, 2023). "Depending on the cell type, CEACAM1, CEACAM5, and CEACAM6 play pivotal roles in particular aspects of cancer biology and immunology." (PMID 36741860, 2023). "Elevated serum levels of soluble MICA and soluble CEACAM-5 and CEACAM-6 have been correlated with impairment of NK cell activity, cancer progression and metastasis." (PMID 36991390, 2023). "The carcinoembryonic antigen‐related adhesion molecules (CEACAMs) are a large family, among which CEACAM5 (CEA) and CEACAM6 are recognized as related to cancer processes." (PMID 36082960, 2023). "Differential expression analyses comparing cancer areas of rHGP and dHGP revealed established CRC cell markers, such as FABP1, CEACAM5, CLDN3, EPCAM and S100A10 in the rHGP (Supplementary Spreadsheet 1)." (PMID 36691028, 2023). "Other than mucins, glycoproteins CEA (carcinoembryonic antigen, also known as CEACAM5) and PSA (prostate-specific antigen) are classic serum biomarkers in a majority of carcinomas." (PMID 37509200, 2023). "Cancer cells in the S components upregulated SOX4 and CEACAM5 and downregulated pro-inflammatory factors such as SCGB1A1 and SFTPC in comparison with cancer cells in the GG components." (PMID 35874770, 2022). "NEO-201 has different mechanisms of action to kill target cancer cells, including ADCC, CDC and the blockade of the CEACAM5/CEACAM1 immune checkpoint inhibitory pathway." (PMID 36291783, 2022). "Although the proteome profile assay showed favorable results by modulating Decorin and M-CSF proteins, our analysis also demonstrates an up-regulation of the cancer-related proteins AXL, CEACAM-5, and SNAIL due to the effect of the drugs." (PMID 34641286, 2021). "Their role as therapeutic target has been further explored, mainly throughout investigational agents targeting CEACAM1, CEACAM5 or CEACAM6, the ones best characterized in cancer processes." (PMID 33509252, 2021). "By western blotting we found that mAb 6G5j detected endogenously expressed CEACAM1, CEACAM5 and CEACAM6 in lysates of epithelial cell lines derived from gastric (MKN45) and colon (HT29, Caco-2) cancer cell lines." (PMID 32064046, 2020). "The elevated expression of CD66e, which is also known as the carcinoembryonic antigen (CEA) or CEACAM5, is a common change because it is a widely expressed receptor in human carcinomas." (PMID 32974184, 2020). "The majority of Luminal B (7 out of 11 carcinomas, 63%) and HER2-enriched (12 out of 16, 75%) tumors were also positive for CEACAM5." (PMID 33196697, 2020). "A literature search showed that many of these altered genes, such as IGF2, FAM83A, CEACAM5 and CEACAM6, STC1 and MSMP, play a role in PCa or other types of cancer." (PMID 31500347, 2019).
cancer (continued). "CEACAM5 (often only abbreviated as CEA) is expressed in normal epithelial cells and overexpressed in the majority of carcinomas including lung carcinomas." (PMID 31357969, 2019). "Moreover, whether KRAS status or mutations of other cancer driver genes in CRC patients (TCGA database) might have led to lack of CEACAM5 interaction with the other studied genes (CEACAM1, CEACAM6 and EPHA2) will need further investigation." (PMID 29262644, 2017). "Our findings raise the question of whether fluctuations in serum CEACAM5 reflect EMT and rEMT processes in both primary tumors and metastatic sites, contributing to cancer dissemination and drug resistance under EGFR‐TKI treatment." (PMID 40856433, 2025). "Whether serum CEACAM5 fluctuations reflect EMT and rEMT in primary tumors and metastatic sites to enable cancer cell dissemination and proliferation under EGFR‐TKI treatment and latter drug resistance requires further investigation." (PMID 40856433, 2025). "The carcinoembryonic antigen (CEA, also known as CD66e and CEACAM-5) is a cell surface glycoprotein commonly overexpressed and released by many solid tumors, playing an autocrine role in cancer cell survival and differentiation." (PMID 39235446, 2025). "Although we also found enrichment of CEACAM5, we focused further studies on CEACAM6 as it was more strongly correlated with acid resistance and had been less extensively explored as a target for cancer therapy." (PMID 38502695, 2024). "Indeed, both CEACAM5 and CEACAM6 molecules have been reported to be highly overexpressed in multiple types of cancer." (PMID 38279989, 2024). "In this review, we explore current knowledge surrounding CEACAM1, CEACAM5, and CEACAM6, highlight their pathological significance in the areas of cancer biology, immunology, and inflammatory disease, and describe the utility of murine models in exploring questions related to these proteins." (PMID 36741860, 2023). "High expression of ITGB1, CAV1 and low expression of CRYBA1, CEACAM5 were observed in all, suggesting the lack of anchorage-independent growth of the two cancer-derived cells is due to different mechanisms than lack of anoikis resistance." (PMID 37264224, 2023). "Carcinoembryonic antigen-related cell adhesion molecule 5 (CEACAM5), alternatively known as CD66e (Cluster of Differentiation 66e), belongs to the carcinoembryonic antigen (CEA) gene family, and it is involved in cell adhesion, signaling, and the promotion of cancer progression and metastasis." (PMID 38001628, 2023). "Interestingly, the expression of CEACAM5 and 6 is upregulated by SMAD3-mediated TGF-β signaling, suggesting a link between the metastatic properties of TGF-β in cancer and CEACAMs." (PMID 36741860, 2023). "In addition to ADCC, NEO-201 has different mechanisms of action to kill cancer cells expressing its target antigen, including CDC and the blockade of the CEACAM5/CEACAM1 immune checkpoint inhibitory pathway." (PMID 36991390, 2023). "Although several mAbs against CEACAM-5 have been found to be effective in diagnosis and therapy of several types of cancers, they failed to interfere with the CEACAM-1-CEACAM-5 interaction." (PMID 35804808, 2022). "CEACAM5 codes for CEA, which is a well-known intercellular adhesion molecule that is known to be over-expressed in a majority of carcinomas, and plays important roles in cancer invasion and metastasis." (PMID 32884102, 2020). "No expression of integrin αvβ6, CEACAM5 and mesothelin was observed in fibrotic tissue, indicating these are potentially suitable targets for vital cancer cell identification after neoadjuvant therapy." (PMID 33004930, 2020). "In contrast to CEACAM5 and CXCL17, two markers demonstrated lower levels in the plasma of cancer patients: VEGFR2 acts as a cell-surface receptor for vascular endothelial growth factors (VEGFA, VEGFC and VEGFD), and is involved in angiogenesis in both physiological and pathological conditions." (PMID 31357969, 2019).
cancer (continued). "Our data show that anti-human CEACAM5 antibody Col-1 specifically detects 180, 120 and 60 kDa molecules in canine cancer cells which are most likely non-related to the canine CEACAM1-related proteins." (PMID 21436956, 2011). "CEACAM5 has been shown to be involved in both homophilic (CEA to CEA) and heterophilic (CEA binding to non-CEA molecules) interactions, suggesting to some that it is an intercellular adhesion molecule involved in cancer invasion and metastasis." (PMID 17201906, 2007). "Targeting CEACAM5 and/or CEACAM6 may therefore be a novel method of modulating cancer cell chemosensitivity and apoptosis." (PMID 17201906, 2007). "However, the epithelial cells in polypoid structures observed in cultures with conditioned media from metaplasia- or cancer-derived fibroblasts strongly expressed CEACAM5 at the apical side with weak or negative AQP5 expression." (PMID 37196797, 2023). "Importantly, this persistent outlier status was observed across three distinct late stage cancer types: lung, breast, and pancreatic, suggesting pre-diagnosis overexpression of CEACAM5 is not tissue-specific, but rather implicating it with metastasis." (PMID 33004987, 2020). "Increasing the expressions of either CEACAM1 or CEACAM5, the ligand for NK CEACAM1, did not affect the killings against cancer cells by CD56+CD16+ NK cells, since these cells do not express CEACAM1." (PMID 21731662, 2011). "KRT19, CEACAM5, EPCAM, DSG3, SFTPA, SFTPC and SFTPB mRNA levels were initially validated by real-time reverse transcription PCR-based quantification in 16 NSCLC tumors and 22 LNs and 12 PB samples from individuals without known cancer." (PMID 23671585, 2013).
adenocarcinoma (63 papers, 2007 to 2025). A common cancer characterized by the presence of malignant glandular cells. "In contrast to TROP2, CEACAM5 displayed a negative correlation with AR in CRPC–adenocarcinoma and was expressed in all NEPC clusters, suggesting that CEACAM5 is an actionable target for non–AR–driven disease." (PMID 38645034, 2024).
gastrointestinal tumors (15 papers, 1983 to 2026). "The ongoing advancement of ADCs targeting CLDN18.2, TROP2, and CEACAM5 indicates that this therapeutic category will continue to expand across gastrointestinal neoplasms." (PMID 42042562, 2026). "Patients with known CEACAM5-positive gastrointestinal tumors suggestive of lung metastasis were selected as proof-of-principle positive controls." (PMID 36705924, 2023). "The trial using CEACAM5-CAR T-cells for gastrointestinal tumors was closed prematurely due to poor efficacy and toxicities." (PMID 30736426, 2019).
infection (10 papers, 2011 to 2024). The state of being infected such as from the introduction of a foreign agent such as serum, vaccine, antigenic substance or organism. "The S protein of MERS-CoV uses Dipeptidyl peptidase 4 (DPP4/CD26) and carcinoembryonic antigen-related cell adhesion molecule 5 (CEACAM5) as attachment or entry receptors for infection." (PMID 33375175, 2020). "Furthermore, members of the CEACAM family are already upregulated upon infection by different influenza virus strains, as recently also shown for CEACAM1 and CEACAM5." (PMID 30973879, 2019).
bacterial infection (4 papers, 2013 to 2022). "Further, the data suggest a role for CEACAM1 and CEACAM5 in the phenomenon of increased host susceptibility to bacterial infection upon viral challenge in the human respiratory tract." (PMID 23941132, 2013). "Besides, in the human respiratory tract, CEACAM1 and CEACAM5 increase the host susceptibility to bacterial infection upon viral challenge." (PMID 34217339, 2021). "In adults with severe asthma, bronchial epithelial CEACAM5 expression and gene signatures typical of the inflammatory airway response driven by bacterial infection are upregulated compared to healthy controls." (PMID 35538891, 2022). "CEACAM receptors, including CEACAM5, have been implicated in host defense against bacterial infections, particularly Moraxella catarrhalis and nontypable Haemophilus influenzae." (PMID 35538891, 2022). "Therefore, CEACAM5 in the bronchial epithelium may be driving the increase in exacerbations noted in the FEs due to bacterial infection." (PMID 35474304, 2022).
CEACAM5 also shares sentences with these, for which no sentence is quoted: prostate carcinoma (63 papers); rectal cancer (43); hepatocellular carcinoma (33); medullary thyroid carcinoma (31); anemia (22); Pleural effusion (18); pancreatic adenocarcinoma (12); Hypertension (9); thyroid cancer (8); cholangiocarcinoma (7); lymphoma (7); mesothelioma (7); multiple myeloma (7); neuroendocrine tumor (7); tuberculosis (7); benign tumors (6); bone metastasis (6); colorectal (6); esophageal cancer (6); glioblastoma (6); hepatitis B (6); liver disease (6); metastasis (6); mucinous neoplasm (6); neuroblastoma (6); digestive system cancer (5); esophageal squamous cell carcinoma (5); intrahepatic cholangiocarcinoma (5); Lymphatic Metastasis (5); oral cancer (5).
A further 256 diseases each share a sentence with CEACAM5 in 5 papers or fewer.